INS (insulin)
Diseases named in the same sentence as INS in open-access papers (continued):
Sharing a sentence is not in itself a finding about the gene and the disease.
diabetes (continued). "Over time, insulin hypersecretion will not be enough to control the blood glucose levels in the normal range, which goes through a continuum of pre-diabetes then to overt diabetes." (PMID 36837914, 2023). "Individuals with diabetes who are not receiving proper insulin treatment, if receiving any at all, will likely be hit harder by a positive COVID-19 diagnosis than those who follow regular schedules and guidelines outlined by a health provider." (PMID 36673730, 2023). "Intraperitoneal insulin and glucose tolerance (week 30) were not different between Cndp1-KO and WT mice with diabetes and normal glucose homeostasis, on ND and HFD, respectively." (PMID 37372000, 2023). "We mainly focus on mechanisms and clinical outcomes of type 2 diabetes mellitus (T2DM), address the apparent paradox of how impaired neuronal insulin can protect from the development of neurodegenerative disorders and propose astrocytic insulin signalling as a new target to explore." (PMID 36901787, 2023). "In one study, stevia did not significantly change the blood glucose, insulin, and HbA1c levels or body weight after 8 weeks of daily consumption among type 2 diabetes mellitus patients." (PMID 38276259, 2023). "Insulin resistance can be present, but diabetes mellitus can never happen if adequate insulin secretion exists." (PMID 37371950, 2023). "There are many types of diabetes, of which type 2 diabetes mellitus (T2DM) is an increasing health problem worldwide due to the body’s inability to produce insulin or use insulin from the pancreas, and insulin resistance is a major underlying pathophysiology of T2DM." (PMID 36983737, 2023). "Contrary to systems that mimic the human physiology of the glucose-insulin regulation system, data-driven glucose prediction does not require comprehension of the physiology of diabetes." (PMID 38161783, 2023). "First, clinical patients with diabetes are treated with hypoglycaemic agents, but the rats were not treated with insulin." (PMID 35895245, 2023). "Beneficial effects in lowering the serum levels of ALT and GGT and improving insulin sensitivity were proven for 4-week treatment with PX-104 at a dose of 5 mg daily in patients with NAFLD diagnoses without diabetes mellitus." (PMID 36902639, 2023). "Canine diabetes, like human diabetes, is divided into two types: type 1 diabetes and type 2 diabetes, with the former being insulin-dependent and the latter being non-insulin-dependent." (PMID 37891946, 2023). "Previous studies of the genetic determinants of insulin resistance in humans without diabetes have predominantly used fasting samples of glucose and insulin, levels of which are largely determined by hepatic insulin sensitivity." (PMID 37291194, 2023). "The low fasting blood glucose and insulin levels in EPI pigs treated with amylase, even together with a high level of GLP1, could suggest some sort of inhibition or slowing down of diabetes development in individuals with high amylase secretion." (PMID 38003366, 2023). "Evidence‐based strategies for simplifying multiple daily insulin injection (MDI) treatment in overtreated people with type 2 diabetes mellitus are still lacking." (PMID 36461758, 2023). "Type 1 diabetes mellitus (T1D) is a condition resulting from autoimmune destruction of pancreatic β cells, leading patients to require lifelong insulin therapy, which, most often, does not avoid the most common complications of this disease." (PMID 37391848, 2023). "Diabetes develops when the connection between the pancreas and insulin is disrupted and when insulin is not used." (PMID 37830554, 2023). "Diabetes mellitus (DM) is a disease in which the body’s cells can no longer utilize the insulin produced by the pancreas, or the pancreas can no longer produce enough insulin." (PMID 37240580, 2023). "Diabetes has a significant negative impact on diet, and the same results are seen in patients treated with OADs or insulin." (PMID 37113185, 2023).
diabetes (continued). "Diabetes is a chronic, life-threatening disease in which the body either does not make enough insulin or has developed insulin resistance." (PMID 37104015, 2023). "TyG is considered as a novel indicator of IR, but previous study found that a significant number patients with fatty liver remained insulin sensitive and 37% of these patients presented no metabolic syndrome, prediabetes or diabetes." (PMID 36742412, 2023). "Interestingly, among the most enriched KEGG pathways, we found “Insulin signaling pathway” and “AGE-RAGE signaling pathway in diabetic complications”, thus suggesting a putative role of the microRNAs of interest in the diabetes development." (PMID 37945677, 2023). "We hypothesized that this deletion prevents expression of SDF2L1 and contributes to the pathophysiology of diabetes in CDs/y by impairing UPR, enhancing ER stress, and preventing CDs/y from secreting sufficient insulin upon demand." (PMID 36674879, 2023). "The impact of sex hormone dynamics on insulin sensitivity and glucose metabolism is subject of constant scientific debate.21, -23 Variations in insulin sensitivity throughout the menstrual cycle have been previously studied in women without diabetes." (PMID 35254146, 2023). "In adipose tissue of people with morbid obesity who were insulin-resistant (with half of this cohort also having diabetes), AMPK activity was lower than in those who were BMI-matched but insulin-sensitive (i.e., without diabetes)." (PMID 36854023, 2023). "The disease presentation was atypical in the proband who had neonatal hypoglycemia on the 3rd day of life (glucose level was 2.1 mmol/L), and despite developing diabetes at 5 months, did not start insulin treatment until 2 years of age." (PMID 36398453, 2023). "In absence of significant time x group interaction, additional comparison between baseline and post-training levels of glucose and insulin metabolism also showed no improvement in patients with (p = 0.220–0.910) and without diabetes (p = 0.713–0.953)." (PMID 36918949, 2023). "Diabetes is a long-term medical condition that arises when the pancreas fails to produce adequate insulin or when the body cannot utilize the insulin it produces effectively." (PMID 38202676, 2023). "In 2021, 13% of deaths in Mexico were due to diabetes, and of the deceased, 74.9% were not insulin dependent." (PMID 36761221, 2023). "Diabetes mellitus is a severe and chronic disease characterised by metabolic disorders in which the pancreas either fails to produce insulin, or the body cannot effectively utilise the insulin produced." (PMID 37953921, 2023). "As the IR key metagenome can be mapped to GWAS-identified genetic loci of diabetes, this metagenome is unlikely to be merely an acquired pathophysiological adaptation to impaired insulin signal transduction; rather, it is a primary genetic defect." (PMID 36979367, 2023). "For instance, SOCS-1 and SOCS-3 may inhibit insulin activity and contribute to insulin resistance, while SOCS-6 and SOCS-7 seem to have a protective role against diabetes." (PMID 37701031, 2023). "A meta-analysis on healthy adults diagnosed with MetS without diabetes showed that glucose-insulin mechanism did not improve following supervised exercise." (PMID 37234057, 2023). "Empagliflozin improved insulin sensitivity indexes in patients with a recent myocardial infarction or unstable angina, without heart failure, and with newly detected, drug naïve diabetes or impaired glucose tolerance." (PMID 37568149, 2023). "In particular, the adjusted excess mortality vs patients without diabetes was 1.3-fold in diabetic patients not receiving insulin and 2.1-fold in those on insulin." (PMID 35976428, 2023). "In pregnancy complicated by diabetes (GDM or T2DM), metformin improves maternal glycemic control and may reduce insulin dose." (PMID 37401946, 2023).
diabetes (continued). "Therefore, CGM is recommended for patients with preexisting diabetes in pregnancy (especially T1DM complicated with pregnancy), GDM requiring insulin treatment, large blood glucose fluctuations, and possible nighttime hypoglycemia." (PMID 37680884, 2023). "Although the mechanisms by which insulin resistance contributes to low HDL-C are known, there are also indications that low HDL-C may actually promote the development of diabetes and that HDL-C elevation can increase insulin sensitivity in peripheral tissues." (PMID 37106164, 2023). "Type-2 diabetes mellitus (T2DM) is a common but detrimental condition that arises from excessive hyperglycemia, leading to either insulin resistance or damage to the B-cells that produce insulin in the pancreas." (PMID 38161953, 2023). "Type 2 diabetes, the most common type of diabetes, arises when the body grows resistant to insulin or does not produce enough of it." (PMID 36673694, 2023). "Baseline characteristics including BMI, duration of diabetes, and insulin requirement did not significantly affect A1C reduction when GLP-1 RA was added." (PMID 37589043, 2023). "Type 2 diabetes mellitus is categorized by symptoms like reduced insulin secretion, non-functioning of the beta cell of pancreas, reduction in the mass of the beta cells and failure in the progression of the beta cells." (PMID 38034631, 2023). "Diabetes mellitus is a debilitating, chronic condition that develops when the pancreas does not produce enough insulin or the body cannot effectively utilize it." (PMID 37059974, 2023). "Insulin is a widely prescribed glucose-lowering agent especially in patients affected by type 1 diabetes mellitus (T1DM) as well as in some patients with Type 2 diabetes mellitus." (PMID 38146457, 2023). "So, a considerable number of patients with diabetes need insulin therapy to maintain their glucose at a near-normal level." (PMID 37174907, 2023). "Adjusting for insulin pump use, frequency of glucose monitoring, and depressed mood for the T1D group and for diabetes medications and depressed mood for the T2D group did not change the results in the SEARCH study." (PMID 37145592, 2023). "Diabetes occurs when the pancreas does not produce enough insulin or does not process insulin properly." (PMID 37893825, 2023). "Diabetes is classified into two types: type 1 diabetes (T1DM), which is an autoimmune illness characterized by insulin insufficiency, and type 2 diabetes (T2DM), which is characterized by inadequate insulin action." (PMID 37894680, 2023). "Diabetes is a chronic condition that develops when either the pancreas does not create enough insulin or when the body does not utilize the insulin that is produced properly." (PMID 36922857, 2023). "The previous PREFER in AF analysis had also shown the much less obvious finding that the occurrence of thromboembolic events in diabetic patients not receiving insulin is similar to that of patients without diabetes." (PMID 35976428, 2023). "Hence, the purpose of this study was to explore the insulin injection practice, and HRQOL of adult diabetes patients who are on insulin at the diabetes clinic of TASH." (PMID 37143082, 2023). "This requires continuous and diligent diabetes care by patients and their caregivers, including administering insulin, frequent self-monitoring of blood glucose (SMBG), dietary compliance, and adjusting insulin doses according to meals and other factors." (PMID 36873812, 2023). "Given the prevailing challenges in clinical 18F-FDG-PET imaging for patients with diabetes, this study aimed to compare the effects of SGLT2 inhibitors and insulin, and to provide clues for diabetic patients to choose appropriate hypoglycemic drugs in 18F-FDG PET imaging diagnosis." (PMID 37884546, 2023).
diabetes (continued). "In the current study, our data suggested, for the first time, PHPB cloud improves diabetes-induced cognitive impairment in type 2 diabetic KK-Ay mice probably via inhibiting the generation of the AGEs and subsequently modulating SIRT1/insulin signaling pathway and reducing oxidative stress." (PMID 37259448, 2023). "On the contrary, the National Institute for Health and Care Excellence (NICE) guidelines recommend using metformin as a first-line agent in women whose diabetes is not adequately controlled by diet, before the institution of insulin therapy." (PMID 36327019, 2023). "Aspart, glargine, and detemir are all safe alternatives for treating diabetes during pregnancy; in this research conducted, these insulin analogs did not increase difficulties for mothers or fetuses." (PMID 38021940, 2023). "According to this recommendation, we observed that the prescriptions of insulin therapy increased significantly during the hospitalization of patients with diabetes in internal medicine and geriatric non-ICU wards." (PMID 36964858, 2023). "CCL4 was upregulated in both people with T1D and T2D, and its inhibition had a protective effect on pancreatic beta-cells, increased insulin sensitivity, and delayed the progression of hyperglycaemia, suggesting the critical role of CCL4-related inflammation in the progression of diabetes." (PMID 36674502, 2023). "Type 2 diabetes mellitus (T2DM) is a chronic metabolic disorder in which the body cannot secrete enough insulin or does not respond appropriately to insulin." (PMID 37960343, 2023). "Regarding the medication use of our population, participants took only oral hypoglycemic agents for diabetes control, and hence those who were on insulin therapy were not included." (PMID 37674617, 2023). "A 16-year-old boy was newly diagnosed with diabetes and was using insulin 3–4 times a day, with no control of his blood sugar." (PMID 37353797, 2023). "For individuals currently using a regular insulin pump and insulin pen therapy, leveraging CGM-based glucose prediction can make more informed decisions regarding their diabetes management, including adjusting insulin doses or prospectively treating hypoglycemia." (PMID 37837098, 2023). "In keeping with this, it seems that IR or diabetes are not pre-requisites for antidepressant response to insulin sensitizers." (PMID 36347837, 2022). "Thus, PTEN suppression in liver and fat improved glycaemia and insulin sensitivity in type 2 diabetes mellitus (T2DM) mice, protecting diabetic mice from developing diabetes." (PMID 35282439, 2022). "Another study compared the salivary microbiome of healthy patients, patients with type 2 diabetes mellitus without treatment, and patients with diabetes treated with metformin or a combination of insulin and other drugs." (PMID 35464780, 2022). "On the other hand, it was observed that, among the patients without diabetes, a significant number of patients were started on insulin therapy (199 (24.4%)), while others were started or continued on oral hypoglycemic agents (0.9% and 0.5%)." (PMID 36498037, 2022). "Diabetes mellitus is a chronic metabolic disorder characterized by a lack of insulin action and/or generation." (PMID 36557843, 2022). "In contrast, researchers gave a 4-hour insulin intervention to healthy volunteers with normal glucose tolerance and no history of diabetes, took biopsies of their lateral femoral muscles, and discovered noticeably elevated levels of related inflammatory genes." (PMID 36589857, 2022). "The proportion of patients with diabetes was similar, but slightly more patients without AF were treated with insulin for their diabetes (compared with those with AF)." (PMID 36017729, 2022). "The significant role of GLUT4 in insulin-regulated uptake of glucose labels GLUT4 as an important member of the normal glucose homeostasis process and consequently as a key player in T2DM type of diabetes and insulin resistance." (PMID 35356248, 2022).
diabetes (continued). "The traditional opinion that pancreatic β cells disappear completely and no endogenous insulin production in longstanding diabetes has been drastically changed based on the detection of persistent C-peptide secretion in individuals with long-term T1DM." (PMID 35311607, 2022). "Thus, harnessing this insulin-independent mechanism (in combination with insulin therapy) is anticipated to reduce DKA incidence and improve management of diabetes." (PMID 35840613, 2022). "Prospective studies to date have shown that half of patients with diabetes will develop PAD within 30 years of diagnosis, with reduced glomerular filtration rate, female gender, and the need for concomitant insulin therapy and oral antidiabetic drugs being among the main associated risk factors." (PMID 36292188, 2022). "Additionally, we investigated if TRDI elevated insulin signaling in these mice; IRS-1, PDK-1, and Akt were phosphorylated in the STZ-induced diabetes plus TRDI group (G4)." (PMID 35883721, 2022). "Diabetes mellitus [DM] is a progressive metabolic disorder identified by severe hyperglycemia correlated with compromised, lipids, carbohydrates and protein metabolism, insufficient insulin regulation or diminished response to physiological effects of insulin production by pancreatic β-cells." (PMID 36404859, 2022). "Lastly, despite available insulin prescriptions, we opted not to adjust for this, but to adjust for gestational diabetes and diabetes mellitus to include more observations and avoid collinearity in our analysis." (PMID 35130922, 2022). "Type 1 diabetes mellitus is primarily an autoimmune condition, where pancreatic beta cells are destroyed by the immune system and can no longer synthesize insulin, leading to hyperglycemia." (PMID 35887304, 2022). "The other 10% corresponds to type 1 diabetes mellitus (T1DM), a chronic, autoimmune disease, where immune cells, mainly T cells, attack, and destruct insulin-producing β pancreatic cells, thus leading to a defect in insulin production." (PMID 36403025, 2022). "Unlike FDG-PET, BMIPP SPECT is less affected by blood substrates (glucose, cholesterol, fatty acids, insulin, etc.), and has the advantage that it can be evaluated both in cases with diabetes or dyslipidemia and in noncomplicated cases." (PMID 34822103, 2022). "They indicated that dementia patients were less likely to receive new diabetes medications and they had higher insulin dispensation ratio than non-dementia controls." (PMID 35197840, 2022). "In ICU patients, temporary hyperglycemia commonly occurs, also in non-diabetic patients, thus patients without diabetes, and obviously those with diabetes, are often given insulin to maintain near normoglycemia." (PMID 36198307, 2022). "The diagnosis of insulin sensitivity and type 2 diabetes mellitus in cats is not the same as in humans." (PMID 36248900, 2022). "β-cell-specific Nova1 or Bim deficiency failed to affect diabetes development in response to MLD-STZ-induced β-cell dysfunction and death evidenced by unaltered blood glucose levels and pancreatic insulin content." (PMID 36145242, 2022). "In the present study, we selected db/db mouse, a model of type II diabetes as the research object, whose genetic background is C57BL/6 mouse diabetes gene knocked out and even insulin intervention fails to control hyperglycemia." (PMID 36312255, 2022). "Unlike Western populations, pre-diabetes in the Japanese population is characterized by both relatively low insulin secretion and insulin resistance." (PMID 35010830, 2022). "FXR activation can regulate glucose-induced insulin transcription and secretion through genomic and non-genomic activities and can delay the occurrence of diabetes and hyperglycemia." (PMID 36091227, 2022). "The share of energy contributed by protein (eggs and omelets, cold cuts and cured meats) and vegetables (tomatoes and lettuce) was also greater among the group reporting taking insulin compared with participants without diabetes." (PMID 36014790, 2022).